KL (klotho)
Description:
Exhibits beta-glucuronidase activity in vitro despite lacking canonical catalytic Glu residues of glycosyl hydrolase 1 family enzymes (By similarity). Hydrolyzes steroid beta-D-glucuronides including estradiol-3-beta-D-glucuronide, estrone-3-beta-D-glucuronide and estriol-3-beta-D-glucuronide (By similarity). Essential for the interaction between FGF23 and FGFR1 and for FGF23-mediated regulation of renal vitamin D and phosphate homeostasis (By similarity). The Klotho peptide generated by cleavage of the membrane-bound isoform may be an anti-aging circulating hormone which would extend life span by inhibiting insulin/IGF1 signaling.
Synonyms: KLA; HFTC3
Tractability: Antibody: UniProt places it where antibodies can reach, with high confidence; its Gene Ontology location is reachable by antibodies, with high confidence; UniProt predicts a signal peptide or a membrane-spanning region.
Target class: Enzyme; Hydrolase
Gene: Protein-coding gene on chromosome 13 (33,016,423 to 33,066,143, forward strand). Ensembl gene ENSG00000133116.
Subcellular location: Cell membrane (Isoform 1); Apical cell membrane; Secreted (Isoform 2); Secreted (Klotho peptide)
Pathways (Reactome):
Signal Transduction: Downstream signaling of activated FGFR1; FGFR1c and Klotho ligand binding and activation; FRS-mediated FGFR1 signaling; Negative regulation of FGFR1 signaling; PI-3K cascade:FGFR1; PI3K Cascade; PI5P, PP2A and IER3 Regulate PI3K/AKT Signaling; PIP3 activates AKT signaling; Phospholipase C-mediated cascade: FGFR1; RAF/MAP kinase cascade; SHC-mediated cascade:FGFR1
Disease: Constitutive Signaling by Aberrant PI3K in Cancer
Gene Ontology:
Molecular function: fibroblast growth factor binding; beta-glucosidase activity; beta-glucuronidase activity; fibroblast growth factor receptor binding; hydrolase activity, hydrolyzing O-glycosyl compounds
Biological process: positive regulation of bone mineralization; fibroblast growth factor receptor signaling pathway; carbohydrate metabolic process; negative regulation of systemic arterial blood pressure; norepinephrine biosynthetic process; response to activity; response to angiotensin; response to fibroblast growth factor; response to vitamin D
Cellular component: extracellular exosome; extracellular region; plasma membrane; apical plasma membrane
Genetic constraint (gnomAD): Loss-of-function variants: 59 observed, 79.94 expected, observed/expected ratio (o/e) 0.74, 90% interval 0.6 to 0.92. The upper end of that interval is the gene's LOEUF score, 0.92, which puts it in group 3 of 6, group 1 being the genes least tolerant of losing a copy. Missense variants: 1,147 observed, 1,224.7 expected, observed/expected ratio (o/e) 0.94, 90% interval 0.89 to 0.98. Synonymous variants: 479 observed, 482.39 expected, observed/expected ratio (o/e) 0.99, 90% interval 0.92 to 1.07.
Homologues: Orthologues: chimpanzee KL (99% identical), macaque KL (97% identical), dog KL (88% identical), mouse Kl (86% identical), rabbit KL (86% identical), rat Kl (85% identical), tropical clawed frog kl (64% identical), guinea pig KL (62% identical), zebrafish kl (50% identical), Drosophila melanogaster CG9701 (17% identical), Caenorhabditis elegans klo-2 (15% identical), Caenorhabditis elegans klo-1 (14% identical). Paralogues in human: KLB (45% identical), LCT (38% identical), LCTL (21% identical), GBA3 (19% identical).
Diseases named in the same sentence as KL in open-access papers:
KL is named in the same sentence as 400 diseases in open-access papers, as found by Europe PMC text mining. Sharing a sentence is not in itself a finding about the gene and the disease. The quoted sentences say what the papers report.
chronic kidney disease (251 papers, 2012 to 2026). Impairment of the renal function secondary to chronic kidney damage persisting for three or more months. "Seventh, chronic kidney disease, which is associated with a reduced lifespan, is associated with reduced expression of the anti-aging factor Klotho and Klotho-deficient mice have a prolonged QTc and a reduced lifespan." (PMID 41745334, 2026). "Klotho expression is downregulated in conditions associated with muscle wasting, including aging, chronic kidney disease, and myopathy." (PMID 40869307, 2025). "Consistently, Klotho levels in humans decline with age and age-related diseases, such as chronic kidney disease, and reductions in Klotho levels are associated with worse cognition in older people and an increased risk of all-cause mortality." (PMID 41393109, 2025). "Reduced serum Klotho levels have been associated with age-related diseases, including chronic kidney disease (CKD), cardiovascular disease (CVD), and metabolic syndrome." (PMID 40969602, 2025). "In humans, higher Klotho levels are associated with reduced risks of chronic kidney diseases (CKD), cardiovascular diseases (CVD), and mortality." (PMID 38501099, 2024). "On the other hand, the anti-aging hormone Klotho has been long implicated in the pathophysiology of Chronic Kidney Disease (CKD), with seminal studies demonstrating a reduction in its expression with CKD progression." (PMID 38786957, 2024). "In humans, klotho deficiency is involved in the pathogenesis of various aging-related disorders, including cardiovascular disease, stroke, and chronic kidney disease." (PMID 38501099, 2024). "Serum Klotho levels showed a decline in individuals with advanced age and those affected by chronic kidney disease, establishing its potential diagnostic significance." (PMID 38213484, 2024). "Declining levels of Klotho are associated with the vascular calcifications seen in chronic kidney disease." (PMID 39861814, 2024). "As mentioned, Klotho is associated with chronic kidney disease and CKD patients were also included in this study population." (PMID 37061530, 2023). "On the other hand, decreases in the serum Klotho concentration were found to be associated with aging and lead to age-related diseases, such as chronic kidney disease (CKD), cardiovascular disease (CVD), diabetes, and a shortened life expectancy." (PMID 36555992, 2022). "Klotho deficiency or aberrant klotho expression has been observed in several age-related disorders, including chronic kidney disease, cancer, and diabetes." (PMID 36221064, 2022). "Loss of Klotho, an anti-aging protein, plays a critical role in the pathogenesis of chronic kidney diseases." (PMID 35064106, 2022). "Evidence indicates that serum Klotho concentration is associated with mortality in patients with chronic kidney disease (CKD)." (PMID 36457804, 2022). "The decline and/or loss of klotho has been associated with human chronic kidney disease, with the levels of klotho positively correlated with eGFR41." (PMID 36434087, 2022). "The expression of longevity-related genes such as Klotho is also closely associated with renal fibrosis, chronic kidney disease, and immune system imbalance [11, 23, 29, 42 to 45]." (PMID 33767585, 2021). "High plasma phosphate and Klotho deficiency contribute to kidney epithelial senescence and kidney fibrosis, an important pathological feature in the aging kidney and chronic kidney disease." (PMID 33767585, 2021). "At the early stage of patients with chronic kidney disease, the decrease of Klotho level will cause a compensatory increase in FGF23." (PMID 34901023, 2021). "Klotho deficiency is a biomarker of kidney disease, and it is also an important pathogenic factor for cardiovascular disease in chronic kidney disease such as myocardial fibrosis and vascular calcification." (PMID 34901023, 2021). "Reduced levels of soluble Klotho have been associated with kidney disease, especially chronic kidney disease (CKD)." (PMID 33585584, 2020).
chronic kidney disease (continued). "High plasma phosphate (Pi) and deficiency of Klotho contribute to aging and kidney fibrosis, a pathological feature in the aging kidney and chronic kidney disease." (PMID 32973510, 2020). "It was shown that Klotho deficiency acts as an early biomarker for kidney damage and contributes to progression of chronic kidney disease." (PMID 32319182, 2020). "Conversely, klotho preservation attenuates chronic kidney disease-associated bone injury in mice via inhibition of histone deacetylase." (PMID 32614356, 2020). "There is good evidence from clinical and experimental studies that both acute and chronic renal failure are associated with reduced expression of Klotho in the kidney, and with reduced sKlotho levels in the blood [43▪▪,44–47]." (PMID 29851418, 2018). "Serum and vascular klotho levels are reduced in patients with chronic kidney disease, and the reduced levels are associated with arterial calcification." (PMID 28771600, 2017). "Klotho is produced by the kidneys; therefore, it was seen to decrease in parallel with the loss of the renal functions in chronic kidney disease." (PMID 25295189, 2014). "Since both chronic kidney disease and oxidative stress itself can reduce klotho, a vicious cycle characterized by low klotho and increased oxidative stress could promote the risk of diabetes." (PMID 40237064, 2025). "Carotid artery intima-media thickness (CIMT) burden, a marker of subclinical atherosclerosis, has been associated with reductions in circulating Klotho levels in chronic kidney disease patients, who show reduced levels of this protein at all stages of the disease." (PMID 37274332, 2023). "In humans, Klotho protein levels typically exhibit a gradual decline after 40 years, a trend further exacerbated by various pathological conditions associated with aging, such as Alzheimer’s disease, chronic kidney disease (CKD), and diabetes." (PMID 37764740, 2023). "The Klotho gene is widely recognized to be involved in the anti-aging process in mammals, and under-expression of Klotho is linked to many diseases, including hypertension, diabetes, and chronic kidney disease." (PMID 37929034, 2023). "Klotho deficiency is implicated in the process of vascular dysfunction or structural abnormalities in the arterial wall, which is closely related to the incidence rate and mortality of chronic kidney disease." (PMID 37261217, 2023). "Loss of the mediator Of cell motility 1 (Memo1) in mice caused kidney disease and a bone disease with diminished osteoblast and osteoclast biomarkers in serum, resembling alterations occurring in adynamic bone disease in humans with chronic kidney disease or in Klotho‐deficient mice." (PMID 36967231, 2023). "Klotho deficiency is observed in acute and chronic kidney disease including DN." (PMID 37261217, 2023). "The greater activation of autophagy induced by Klotho was associated with greater mitigation of ischemia/reperfusion-induced acute kidney injury, and may delay progression from acute kidney injury to chronic kidney disease through clearance of type I collagen." (PMID 34737707, 2021). "Klotho expression abnormalities induces kidney injury and chronic kidney disease, however, the underlying mechanism remains unclear." (PMID 33767585, 2021). "The decrease of Klotho values in renal tissue and urine samples after acute kidney injury was confirmed in animal studies and association of urinary Klotho with nephron function in chronic kidney disease was also reported in human studies." (PMID 33033444, 2020). "Furthermore, Klotho deficiency is strongly associated with human diseases related to aging such as cancer, chronic kidney disease, atherosclerosis, skin atrophy, chronic pulmonary diseases and osteoporosis." (PMID 31346213, 2019).
chronic kidney disease (continued). "Therefore, it has been postulated that massive elevations in circulating levels of FGF23, as found in patients with chronic kidney disease, contribute to associated pathologies by targeting cells and tissues that lack klotho." (PMID 29770125, 2018). "Notably, the renoprotective role of klotho has been implicated in various acute and chronic kidney diseases including DKD, indicating the functional importance of antiaging in DKD." (PMID 28929120, 2017). "Chronic kidney disease (CKD) is associated with a significant decrease in renal Klotho expression." (PMID 29179433, 2017). "However, most researchers consider that the production of klotho is decreased in chronic renal failure and that its deficiency is closely related to the development and progression of renal diseases." (PMID 26813039, 2016). "Chronic kidney disease (CKD) is regarded as a state of Klotho deficiency and FGF23 excess." (PMID 24695641, 2014). "Both acute kidney injury and chronic kidney disease exhibit renal and systemic α-klotho deficiency." (PMID 25084095, 2014). "This study aimed to quantify the association of Klotho and cognitive impairment in chronic kidney disease (CKD) patients with albuminuria." (PMID 37560310, 2023). "Chronic kidney disease (CKD) has been a condition of Klotho deficiency, and animal models of CKD showed the reduced levels of total Klotho gene expression and in kidney tissue, with low soluble Klotho in circulation." (PMID 37228732, 2023). "Soluble Klotho (s-Klotho) is associated with chronic kidney disease (CKD) and aging, but little is known on its relationship with chronic micro- and macro-vascular complications of type 2 diabetes and glycemic control." (PMID 35286490, 2022). "This restoration of Klotho expression was associated with an inhibition of cellular senescence and improvement of kidney function in diabetic mice, suggesting a role of complement in the regulation of klotho in chronic kidney disease, similar to what is observed in acute kidney injury." (PMID 36434087, 2022). "The association of Klotho levels with AoS has also been demonstrated in patients with chronic kidney disease (CKD)." (PMID 34820427, 2021). "Therefore, the present study demonstrates that BSA alters the community structure of the intestinal flora and induces kidney damage and chronic kidney disease in mice and promotes immune activation and chronic inflammation in Klotho-deficient mice with intestinal dysbacteriosis." (PMID 33767585, 2021). "Recent studies have reported that the prevention of Klotho decline and direct supplementation of soluble Klotho are both associated with attenuated renal fibrosis and slowed chronic kidney disease (CKD) progression." (PMID 32054986, 2020). "As such, modulation of Klotho activity is an attractive target for therapeutic intervention in the diseasome of aging; in particular for chronic kidney disease (CKD), where Klotho has been implicated directly in the pathophysiology." (PMID 32982966, 2020). "Disruption of FGF23-α-KL signaling is thought to be an early hallmark of chronic kidney disease (CKD) involving reduced renal α-KL expression and a reciprocal rise in serum FGF23." (PMID 24466013, 2014). "However, it is unclear whether the serum Klotho levels are associated with signs of vascular dysfunction such as arterial stiffness, a major determinant of prognosis, in human subjects with chronic kidney disease (CKD)." (PMID 23431388, 2013). "The downregulation of Klotho in renal injury predicts the progression of chronic kidney disease (CKD)." (PMID 41596204, 2026). "Klotho, an anti-aging protein, has been extensively studied in systemic conditions such as chronic kidney disease and cardiovascular disorders." (PMID 40427517, 2025).
chronic kidney disease (continued). "Furthermore, in relation to nephropathic diseases, reduced Klotho has been associated with increased adverse clinical outcomes in patients with chronic kidney disease (CKD), including elevated creatinine levels, CKD progression and CKD-mineral bone disease." (PMID 40134808, 2025). "The protective role of Klotho in renal disorders has been shown, where Klotho deficiency acted as an early biomarker and therapeutic target in acute kidney injury (AKI) and chronic kidney disease (CKD)." (PMID 41574188, 2025). "The effect of FGF23 is reduced by the decrease in Klotho protein in patients with chronic kidney disease (CKD)." (PMID 41426862, 2025). "The MRA spironolactone has been shown to prevent VC in both chronic kidney disease (CKD) rats and Klotho-deficient mice, likely through attenuation of MR signaling, local inflammation, osteogenic transdifferentiation, and apoptosis." (PMID 41438090, 2025). "The Klotho gene exerts a protective effect on chronic kidney disease by reducing inflammatory responses and improving lipid metabolism." (PMID 41049486, 2025). "Although the regulatory mechanisms of Klotho in systemic conditions such as chronic kidney disease and cardiovascular disorders have been well-established, its specific role in oral and maxillofacial diseases has not been systematically elucidated." (PMID 40427517, 2025). "The soluble form of Klotho (s-Klotho) has been identified as a circulating factor that exerts protective effects against a range of systematic conditions, including chronic kidney disease, interstitial lung disease, and cardiovascular disorders." (PMID 40004457, 2025). "Shenyuan granules inhibit the Wnt/β-catenin pathway by regulating serum soluble Klotho (sKlotho) levels, thereby reducing VC in chronic kidney disease (CKD) models." (PMID 41536360, 2025). "In patients with chronic kidney disease (CKD), the rs495392 polymorphism in the Klotho gene has been associated with decreased odds of atheromatosis progression." (PMID 39702436, 2024). "This, however, would still contradict the large body of literature clearly indicating that decreased Klotho has a strong impact on the progression of chronic kidney disease and renal fibrosis." (PMID 39277686, 2024). "This review will specifically focus on αKlotho, hereafter referred to as Klotho-, due to its potential relevance as a biomarker in chronic kidney disease (CKD)." (PMID 38339121, 2024). "In chronic kidney disease, urinary Klotho levels seem to be inversely related to urinary klotho excretion and have also been demonstrated to be involved in sodium homeostasis." (PMID 39861814, 2024). "Chronic kidney diseases (CKD) results from decreased levels of Klotho and increased levels of FGF23 in the serum." (PMID 39066929, 2024). "Studies have reported a correlation between changes in Klotho levels, the degree of renal function damage, and the prognosis of chronic kidney disease (CKD)." (PMID 38812032, 2024). "Klotho and its cardiovascular implications have been described in the context of chronic kidney disease (CKD) in both experimental and clinical contexts too." (PMID 38787156, 2024). "Phase 2 trials of Klotho protein therapy in chronic kidney disease patients are ongoing, showing acceptable safety and bioactivity profiles thus far." (PMID 38501099, 2024). "Klotho is pertinent to various age-related disorders, including cardiovascular disease, chronic kidney disease,diabetes, and cancer." (PMID 39777219, 2024). "Fibroblast growth factor-23 (FGF-23) and Klotho have been proven to contribute to chronic kidney disease-mineral and bone disorder (CKD-MBD) in patients undergoing hemodialysis." (PMID 39839279, 2024). "Klotho reduces renal fibrosis in several chronic kidney disease models, including the 5/6 nephrectomy, unilateral ureteral obstruction (UUO), and adriamycin nephropathy models." (PMID 39308872, 2024).